RBCK1 (RANBP2-type and C3HC4-type zinc finger containing 1)
Description:
E3 ubiquitin-protein ligase, which accepts ubiquitin from specific E2 ubiquitin-conjugating enzymes, such as UBE2L3/UBCM4, and then transfers it to substrates. Functions as an E3 ligase for oxidized IREB2 and both heme and oxygen are necessary for IREB2 ubiquitination. Promotes ubiquitination of TAB2 and IRF3 and their degradation by the proteasome. Component of the LUBAC complex which conjugates linear ('Met-1'-linked) polyubiquitin chains to substrates and plays a key role in NF-kappa-B activation and regulation of inflammation. LUBAC conjugates linear polyubiquitin to IKBKG and RIPK1 and is involved in activation of the canonical NF-kappa-B and the JNK signaling pathways. Linear ubiquitination mediated by the LUBAC complex interferes with TNF-induced cell death and thereby prevents inflammation. LUBAC is recruited to the TNF-R1 signaling complex (TNF-RSC) following polyubiquitination of TNF-RSC components by BIRC2 and/or BIRC3 and to conjugate linear polyubiquitin to IKBKG and possibly other components contributing to the stability of the complex. The LUBAC complex is also involved in innate immunity by conjugating linear polyubiquitin chains at the surface of bacteria invading the cytosol to form the ubiquitin coat surrounding bacteria. LUBAC is not able to initiate formation of the bacterial ubiquitin coat, and can only promote formation of linear polyubiquitins on pre-existing ubiquitin. The bacterial ubiquitin coat acts as an 'eat-me' signal for xenophagy and promotes NF-kappa-B activation. Together with OTULIN, the LUBAC complex regulates the canonical Wnt signaling during angiogenesis. Binds polyubiquitin of different linkage types.
Synonyms: HOIL-1; C20orf18; RNF54; UBCE7IP3; XAP3; XAP4; RBCK2; ZRANB4; HOIL1; PBMEI; PGBM1
Tractability: PROTAC: UniProt records ubiquitination sites on it; ubiquitination databases record sites on it; its protein half-life has been measured; a small molecule that binds it is known.
Gene: Protein-coding gene on chromosome 20 (407,498 to 432,139, forward strand). Ensembl gene ENSG00000125826.
Pathways (Reactome):
Signal Transduction: Regulation of TNFR1 signaling; TNFR1-induced NF-kappa-B signaling pathway; TNFR1-induced proapoptotic signaling
Immune System: Antigen processing: Ubiquitination & Proteasome degradation
Gene Ontology:
Molecular function: identical protein binding; protein binding; ubiquitin binding; ubiquitin protein ligase activity; ubiquitin-protein transferase activity; ubiquitin ligase activator activity
Biological process: defense response to bacterium; positive regulation of canonical NF-kappaB signal transduction; proteasome-mediated ubiquitin-dependent protein catabolic process; protein linear polyubiquitination; protein polyubiquitination; T cell receptor signaling pathway; positive regulation of apoptotic process; positive regulation of non-canonical NF-kappaB signal transduction; protein ubiquitination
Cellular component: LUBAC complex; cytosol
Genetic constraint (gnomAD): Loss-of-function variants: 44 observed, 63.56 expected, observed/expected ratio (o/e) 0.69, 90% interval 0.54 to 0.89. The upper end of that interval is the gene's LOEUF score, 0.89, which puts it in group 3 of 6, group 1 being the genes least tolerant of losing a copy. Missense variants: 569 observed, 661.79 expected, observed/expected ratio (o/e) 0.86, 90% interval 0.8 to 0.92. Synonymous variants: 306 observed, 271.15 expected, observed/expected ratio (o/e) 1.13, 90% interval 1.03 to 1.24.
Gene-disease validity (ClinGen):
ClinGen rates the evidence that RBCK1 causes each of these diseases.
polyglucosan body myopathy 1 with or without immunodeficiency (autosomal recessive): Definitive. A rare, genetic, glycogen storage disorder characterized by polyglucosan accumulation in various tissues, manifesting with progressive proximal muscle weakness in the lower limbs and rapidly progressive, usually dilated, cardiomyopathy.
Homologues: Orthologues: chimpanzee RBCK1 (99% identical), macaque RBCK1 (99% identical), pig RBCK1 (96% identical), dog RBCK1 (95% identical), mouse Rbck1 (91% identical), rat Rbck1 (91% identical), guinea pig RBCK1 (86% identical), rabbit RBCK1 (78% identical), zebrafish rbck1 (53% identical), tropical clawed frog rbck1 (50% identical). Paralogues in human: SHARPIN (19% identical), RNF216 (18% identical).
Diseases named in the same sentence as RBCK1 in open-access papers:
RBCK1 is named in the same sentence as 72 diseases in open-access papers, as found by Europe PMC text mining. Sharing a sentence is not in itself a finding about the gene and the disease. The quoted sentences say what the papers report.
Immunodeficiency (17 papers, 2015 to 2024). Failure of the immune system to protect the body adequately from infection, due to the absence or insufficiency of some component process or substance. "HOIL-1L/RBCK1 has been identified as a gene that causes autoinflammation with immunodeficiency and/or polyglucosan storage myopathy type 1 (PGBM1)." (PMID 38329126, 2024). "RBCK1 is essential for NF-κB stimulation and mutations in RBCK1 were associated with immunodeficiency." (PMID 34795663, 2021). "Fibroblasts from patients multi-organ autoinflammation, immunodeficiency, and amylopectinosis due to loss of function mutations in RBCK1 and RNF31 exhibited diminished IL1B- and TNF-induced NFκB activation yet monocytes were hyper-responsive to IL1B." (PMID 32687504, 2020). "Genetically determined deficiencies in RNF31 and RBCK1 cause immune deficiency, autoinflammatory disease, and glycogen storage disease in human patients, whereas absence of OTULIN has been reported in six patients with an autoinflammatory syndrome." (PMID 32687504, 2020). "Additionally, as an essential for NF-κB stimulation, RBCK1 mutations are shown to be related to immunodeficiency and tumor-infiltrating immune cells, which proved to be an independent prognostic biomarker in RCC." (PMID 36248876, 2022). "The patients with RBCK1 mutations reported so far vary considerably with respect to their leading clinical presentation (i.e., skeletal muscle, heart muscle, autoinflammation or immunodeficiency)." (PMID 29260357, 2018). "Biallelic LoF mutations in two of the LUBAC component: HOIL-1 (heme-oxidized IRP2 ubiquitin ligase 1; RBCK1) or HOIP (HOIL-1 interacting protein; RNF31), cause LUBAC deficiency, an autosomal recessive disease characterized by severe immunodeficiency, recurrent fever, and polyglucosan myopathy." (PMID 34163478, 2021). "Polyglucosan body myopathy 1 (PGBM1) is a type of glycogen storage disease that can cause skeletal muscle myopathy and cardiomyopathy with or without immunodeficiency due to a pathogenic mutation in the RBCK1 gene." (PMID 33413275, 2021). "Similarly, the association of autoinflammatory disease with both increased and decreased linear ubiquitination and the coexistence of immunodeficiency and autoinflammation in RNF31- and RBCK1-deficient patients seem contradictory." (PMID 32687504, 2020). "Patients with mutations in HOIL1 (RBCK1) present with amylopectinosis-associated myopathy with or without hyper-inflammation and immunodeficiency." (PMID 25599590, 2015). "In this regard, humans with a genetic defect in RNF31 (coding for HOIP) or RBCK1 (coding for HOIL1) developed autoinflammation and immunodeficiency, which overlap with the phenotype observed in the SHARPIN-deficient mice." (PMID 31457011, 2019).
breast carcinoma (13 papers, 2015 to 2024). "Our study implicated the muti-faced function of RBCK1 in different subtype of breast cancers and an interesting therapeutic target for TNBC treatments." (PMID 36280829, 2022). "The chr20p13 genomic deletion spans multiple genes, including RBCK1, whose reduced expression has been shown to be associated with increased tumor cell proliferation and survival, as well as with poor prognosis in breast cancer." (PMID 30838036, 2019). "RBCK1 protein was associated with resistance to endocrine therapy in breast cancer." (PMID 36473847, 2022). "We obtained the expression of RBCK1 in various types of breast cancer in the recognized TCGA database." (PMID 36473847, 2022). "Next, these two siRNAs of RBCK1 were applied to observe their effect on the phenotype of ER-positive breast cancer cells under hypoxic conditions." (PMID 36473847, 2022). "Phenotypic studies of cells report that silencing RBCK1 significantly inhibits the proliferation of breast cancer cells." (PMID 36473847, 2022). "RBCK1 has been reported to be overexpressed in lung adenocarcinoma, breast cancer, colorectal cancer, and renal cell carcinoma, where high RBCK1 expression correlates with an unfavorable prognosis." (PMID 35869046, 2022). "In summary, our study reveals the diversity of RBCK1 function in different subtypes of breast cancers." (PMID 36280829, 2022). "Further studies showed RBCK1 also facilitated luminal type breast cancer growth and endocrine resistance via trans-activation estrogen receptor alpha." (PMID 36280829, 2022). "These interesting findings boost the understanding of the regulation of Hippo/YAP signal transduction, but also reveal the "multifaceted" role of RBCK1 in different subtypes of breast cancer." (PMID 36280829, 2022). "The gene set enrichment analysis plot and KEGG plot demonstrate that RBCK1 consumption in MCF-7 breast cancer cells inhibited the HIF1α signaling pathway and positively correlated with the HIF1α signaling pathway." (PMID 36473847, 2022). "Our study revealed the multi-faced RBCK1 function in different subtypes of breast cancer patients and a promising therapeutic target for TNBC treatment." (PMID 36280829, 2022). "In the current study, we report the E3 ubiquitin ligase RBCK1, which were regarded to facilitate estrogen signaling and luminal type breast cancer progression, exerts the opposite roles in TNBC subtypes." (PMID 36280829, 2022). "TCGA database showed that RBCK1 was moderately elevated in human breast cancers (Fold change = 1.36), while RBCK1 was also elevated all different subtypes compared with normal breast tissue (Luminal type, FC = 1.43; HER2 positive, FC = 1.16; TNBC, FC = 1.07)." (PMID 36280829, 2022). "Previous studies revealed that RBCK1 mainly exerted its function via its ubiquitin ligase function and facilitated luminal type breast cancer cell progression and tamoxifen resistance via estrogen signaling." (PMID 36280829, 2022). "RBCK1 modulates the HIF1α signaling pathway through a post-translational mechanism influencing breast cancer development." (PMID 36473847, 2022). "We found a E3 ubiquitin ligase RBCK1, which is prominently elevated in breast cancer and mainly exhibits carcinogenic effects." (PMID 36473847, 2022). "Previous studies have displayed that the RBCK1 protein regulates the mechanism by which estrogen signaling pathways mediate breast cancer proliferation and progression." (PMID 36473847, 2022). "While ERalpha has already been well documented to play an important role in the etiology and progression of breast cancer, RBCK1, RNF31 and SHARPIN has recently emerged as potential new players in tumorigenesis." (PMID 29763465, 2018). "We have previously reported that RBCK1 mRNA expression correlates positively with ERα mRNA expression in a limited set of ERα-positive breast cancer samples." (PMID 29763465, 2018).
breast carcinoma (continued). "Publicly-available databases have determined that mRNA expression of RBCK1 in breast cancer is substantially higher than that of healthy breast epithelium and that RBCK1 mRNA levels in ER-positive breast cancer tissues were significantly increased compared to ER-negative breast cancer tissues." (PMID 36473847, 2022). "In addition, RBCK1 regulates cell cycle progression and growth in ERα-positive breast cancer cells by facilitating the transcription of ERα and cell cycle protein B1." (PMID 35869046, 2022). "In addition, RBCK1 is highly expressed in pulmonary adenocarcinoma, breast cancer, colon cancer, and renal cell carcinoma." (PMID 35869046, 2022). "Similarly, RBCK1 also exhibits cancer-promoting capabilities in renal cell cancer, colorectal cancer, breast cancer cells, and lung tumors." (PMID 35869046, 2022). "Our results reported in the present study of breast cancer samples from the Iranian population are consistent with the previous study, as we found a significant positive correlation between RBCK1 mRNA expression and ERalpha mRNA expression levels (r = 0.51, p < 0.001)." (PMID 29763465, 2018). "We analyzed the expression distribution of RBCK1 in tumor and normal samples from the TCGA database and GTEx Portal and found the significantly different expression of RBCK1 in pan-cancers, such as bladder cancer, breast cancer, glioma, lung cancer, and liver cancer." (PMID 34795663, 2021). "In breast cancer, MTSS1 interacts with the E3 ligase RBCK1, enhancing RBCK1-mediated ubiquitination and degradation of p65, thereby inhibiting the NF-κB signaling pathway that is essential for the self-renewal of TICs." (PMID 39625546, 2024). "Prior works have depicted that RBCK1 promotes the proliferation of MCF-7 and T47D breast cancer cells with ER-positive expression and shows that this is attributable to the upregulation of ERα gene and protein expression." (PMID 36473847, 2022). "Although RBCK1 is modestly elevated in breast cancer and even elevated in TNBC, RBCK1 relates to good survival in TNBC and negatively correlates with YAP protein level in TNBC samples." (PMID 36280829, 2022). "Our research group has previously shown that RBCK1 promotes proliferation in ERalpha expressing MCF-7 and T-47D breast cancer cells and suggested that this is due to up-regulation of ERalpha gene and protein expression and down-stream target genes." (PMID 29763465, 2018). "Besides the function of RBCK1 in LUBAC complex and NFKB signaling, the function of RBCK1 in breast cancer were extensively studies in recent years." (PMID 36280829, 2022). "Follow-up of patients and evaluation of the expression of RBCK1, RNF31 and SHARPIN with tumor recurrence and overall survival of patients may further shed lights on the prognostic role of this complex on breast cancer." (PMID 29763465, 2018). "Collectively, our findings indicate that up-regulated mRNA expression of RNF31, RBCK1 and SHARPIN could potentially be diagnostic biomarkers of breast cancer and RNF31 might be a drug target for ERalpha-negative breast cancers." (PMID 29763465, 2018).
cardiomyopathy (6 papers, 2017 to 2023). A disease of the heart muscle or myocardium proper. "RBCK1 deficiency is a rare disease that is characterized by onset usually in childhood or adolescence of muscle weakness and rapidly progressive cardiomyopathy." (PMID 27718144, 2017). "Our findings add to the mutational spectrum of recessive cardiomyopathies, supporting inclusion of KLHL24, NRAP and RBCK1 as disease-causing genes." (PMID 36672924, 2023).
colorectal cancer (6 papers, 2021 to 2022). A primary or metastatic malignant neoplasm that affects the colon or rectum. "It has also been confirmed that high expression of RBCK1 is closely associated with cancer-associated fibroblasts (CAFs) in colorectal cancer and tumor-associated macrophages in kidney cancer." (PMID 36473847, 2022). "Overexpression of RBCK1 was reported to be associated with a poor prognosis in colorectal cancer patients." (PMID 36353119, 2022). "Another study demonstrated that RANBP2-type and C3HC4-type zinc finger-containing 1 (RBCK1) protein was over-expressed chemoresistant colorectal cancer patients." (PMID 36550571, 2022). "In that study, they showed colorectal cancer cells cultured with condition media collected from CAFs significantly enhanced stemness and chemoresistance with highly expressed RBCK1 protein in colorectal cancer cells." (PMID 36550571, 2022). "This study indicated that RBCK1 modulated the drug sensitivity of colorectal cancer cells." (PMID 36550571, 2022). "RBCK1 contributes to chemoresistance and stemness in colorectal cancer." (PMID 33816274, 2021).
hepatocellular carcinoma (5 papers, 2022 to 2025). A malignant tumor that arises from hepatocytes. "A recent study also demonstrated experimentally that RBCK1 can significantly inhibit the apoptosis and promote invasion in hepatocellular carcinoma, supporting its role in aggressive tumor behavior." (PMID 41031125, 2025). "However, the role and molecular mechanism of RBCK1 in the occurrence and development of hepatocellular carcinoma are still unclear." (PMID 38214606, 2024). "we found that RBCK1 could bind to 65 proteins, while 43 proteins were found to bind to RBCK1 protein in hepatocellular carcinoma." (PMID 38214606, 2024).
liver cancer (5 papers, 2021 to 2025). An epithelial or non-epithelial malignant neoplasm that arises from the liver. "We also analyzed immune cell infiltration and found that RBCK1 expression was positively correlated with T cells and macrophages, while it was negatively correlated with neutrophils, NK cells, and DCs in liver cancer." (PMID 38214606, 2024). "Through protein interaction analysis, we found 43 proteins interacting with RBCK1 in liver cancer." (PMID 38214606, 2024). "Although RBCK1 plays an important role in liver cancer, its role in liver cancer is not clear." (PMID 38214606, 2024).
renal cell carcinoma (5 papers, 2019 to 2023).
viral infection (5 papers, 2015 to 2025). "The resultant TDP35 enhances nuclear IRF3 levels by degrading Rbck1 pre-mRNA, thus averting the proteasomal degradation of IRF3 during viral infection and selectively promoting antiviral IFN-I production." (PMID 40006907, 2025).
lung adenocarcinoma (4 papers, 2019 to 2024). A carcinoma that arises from the lung and is characterized by the presence of malignant glandular epithelial cells. "With the increasing risk score of patients with lymph node metastasis of lung adenocarcinoma, the expression of high-risk mRNAs (HMMR, B4GALT1, ANGPTL4, EXT1, GPC1, RBCK1, SOD1, AGRN) was obviously upregulated." (PMID 31847905, 2019).
colon carcinoma (3 papers, 2022 to 2024). "Only eight genes (UCN, TRIM, RBCK1, TPM2, CD36, NMB, PPARGC1A, and LGALS4) significantly affected the OS in patients with colon cancer (P < 0.05)." (PMID 35572595, 2022). "In our study, based on the colon cancer immune gene datasets, we used WGCNA to identify 21 immune-related hub genes affecting patients’ OS and constructed IRGPI based on 8 independent OS prognostic factors (UCN, TRIM58, RBCK1, TPM2, CD36, NMB, PPARGC1A, and LGALS4)." (PMID 35572595, 2022).
glycogen storage disease (3 papers, 2021 to 2023). "Bi-allelic variants in the RBCK1 gene, which encodes a ubiquitin ligase, have been associated with glycogen storage disease resulting in childhood or juvenile onset myopathy and a rapidly progressive dilated cardiomyopathy (OMIM: 615895)." (PMID 36672924, 2023). "Polyglucosan body disease (PBD) is a type of glycogen storage disease (GSD) and is mainly caused by mutations in eight different human genes, namely, GYG1, GBE1, RBCK1, PFKM, EPM2A, EPM2B (NHLRC1), PRDM8, and PRKAG2." (PMID 33413275, 2021).